CHD4 (chromodomain helicase DNA binding protein 4)
Diseases named in the same sentence as CHD4 in open-access papers (continued):
Sharing a sentence is not in itself a finding about the gene and the disease.
Intellectual disability (8 papers, 2018 to 2024). "Missense substitutions in CHD4 were found in individuals sharing symptoms including intellectual disability, macrocephaly, hearing loss, distinct facial dysmorphisms, palatal abnormalities, ventriculomegaly, and hypogonadism." (PMID 37938928, 2024). "Conditional, homozygous deletion of Chd4—a chromatin remodeler implicated in intellectual disability and expressed in many cerebellar cell types—in mature granule cells (driven by Gabra6-Cre) caused moderate 3D changes across the mouse genome." (PMID 36865235, 2023). "The characteristic phenotype of individuals with CHD3 mutations overlaps with that reported for de novo mutations in CHD4, in which intellectual disability, macrocephaly, ventriculomegaly, undescended testes, and similar facial features have been reported." (PMID 30397230, 2018). "Finally, pathogenic variants in CHD3 and CHD4 have recently been described in patients with developmental delay, intellectual disability, macrocephaly, impaired speech, and dysmorphic features." (PMID 33944996, 2021). "Mutations of Chd4 and other chromatin remodeling enzymes as well as of proteins closely associated with genome architecture including the cohesin complex cause neurodevelopmental disorders of cognition such as intellectual disability and autism." (PMID 32647123, 2020). "Similar to CHD4, CHD3 mutations, most of which cluster within the ATPase/helicase motif, have been associated with a distinct syndrome characterized by intellectual disability, macrocephaly, impaired speech, and language skills, as well as distinctive facial features." (PMID 37938928, 2024). "CHD proteins play an important role in neurodevelopment, as pathogenic variants in CHD1, CHD2, CHD4, CHD7 and CHD8 have been associated with a range of neurological phenotypes, including autism spectrum disorder (ASD), intellectual disability (ID) and epilepsy." (PMID 29962935, 2018). "SIHIWES or CHD4-NDD is characterized by a highly variable clinical phenotype, but almost all patients have some degree of developmental delay and/or intellectual disability." (PMID 36672520, 2022).
triple-negative breast carcinoma (8 papers, 2019 to 2024). An invasive breast carcinoma which is negative for expression of estrogen receptor (ER), progesterone receptor (PR), and human epidermal growth factor receptor 2 (HER2). "In triple-negative breast cancer (TNBC) and PTC cell lines, CHD4 was significantly associated with the metastatic state and mediated epithelial-mesenchymal transition (EMT)." (PMID 36681835, 2023). "In triple negative breast cancer cells (TNBCs), CHD4 regulates β1 integrin, E-cadherin, and p21 expression to control cell migration, invasiveness, and proliferation through different mechanisms." (PMID 33981601, 2021). "Previous studies revealed that CHD4 suppressed p21 expression owing to its histone deacetylation activity, thus affecting drug response in Triple-negative breast cancer (TNBC) cells." (PMID 31438571, 2019). "In triple-negative breast cancer (TNBC) tissue, chromodomain-helicase-DNA-binding protein 4 (CHD4) promotes the β-catenin nuclear accumulation." (PMID 39223632, 2024). "A recent study showed that CHD4 activates EMT and induces metastatic potential in triple-negative breast cancer cells." (PMID 33419089, 2021).
lung carcinoma (6 papers, 2020 to 2025). "CHD4 mutation rs74790047 was identified as a common exonic mutation connected with lung cancer patients." (PMID 40004553, 2025). "The results revealed that CHD4/6/7/8 was significantly upregulated in multiple datasets in lung cancer compared with normal tissues." (PMID 35467222, 2022). "In this study, the expression of CHD4 was higher in lung cancer than in normal tissues." (PMID 35467222, 2022). "MiR-614 was found to inhibit cell proliferation, CHD4 regulates both proliferative and migratory abilities of NSCLC cells via the RhoA/ROCK pathway, while the role of DPY30 has not yet been clarified in lung cancer." (PMID 40282457, 2025).
Sifrim-Hitz-Weiss syndrome (6 papers, 2020 to 2026). A rare multiple congenital anomalies/dysmorphic syndrome due to CHD4 gene mutations. "Recently, de novo mutations in CHD4 have been implicated in a distinct developmental disorder, ‘Sifrim-Hitz-Weiss’ (SIHIWES) syndrome." (PMID 37445725, 2023). "Our structure also maps CHD4 mutations that are associated with human cancer or the intellectual disability disorder Sifrim-Hitz-Weiss syndrome." (PMID 32543371, 2020). "In contrast, Chd4+/- (heterozygous) mice survive into adulthood but show altered growth, as well as altered neurological, cardiovascular, and reproductive development, similar to what is observed in Sifrim-Hitz-Weiss syndrome in humans." (PMID 41417740, 2025).
papillary thyroid carcinoma (5 papers, 2023 to 2026). "In papillary thyroid carcinomas (PTCs), CHD4 is overexpressed and associated with aggressive features of the tumor, such as proliferation, migration, and epithelial-mesenchymal transition (EMT)." (PMID 41908702, 2026). "Besides HNSCC, previous studies suggested CHD4 as a prognostic marker in papillary thyroid cancer and low CHD4 expression had a beneficial effect on OAS and lower disease recurrence rates in patients afflicted with colorectal cancer." (PMID 38594331, 2024). "Notably, the CHD4 role is also found in papillary thyroid cancer (PTC)." (PMID 40004553, 2025).
rectal cancer (5 papers, 2019 to 2025). A primary or metastatic malignant neoplasm that affects the rectum. "It is concluded that targeting CHD4 will facilitate sensitivity towards PARP inhibitors in rectal cancer cells." (PMID 40004553, 2025). "Among the six relevant RMPs identified in rectal cancer patients, two—CHD4 and ZNF224—were specifically found to be involved in DNA repair and maintenance." (PMID 40149344, 2025). "Analysis of the Gene Expression Omnibus (NCBI-GEO) database-derived microarray datasets (GSE68204) of rectal cancer demonstrated a significant upregulation of CHD4 expression in rectal cancer patients." (PMID 40004553, 2025). "Histological studies, combined with transcriptomic data and protein–protein interaction studies, showed that CHD4 acts as a potential biomarker in the context of rectal cancer." (PMID 40004553, 2025). "Many studies have focused on identifying genes as biomarkers associated with tumor response and survival prognosis of rectal cancer patients with pCRT, such as SERPINB5, CHD4, TCN1, VNN1, EPHA4, PCSK1, and DUOX2 genes." (PMID 33506057, 2021). "We also elucidated the prognostic significance of CHD4 expression in the survival of rectal cancer patients." (PMID 31438571, 2019). "In the in vivo-based approach, the levels of CHD4 protein expression were evaluated in 172 pairs of cancer tissue samples, and adjacent normal mucosa from patients with rectal cancer, who are receiving neo-adjuvant CCRT, followed by surgery." (PMID 31438571, 2019). "To address this question, we next performed immunohistochemical staining of 172 rectal cancer specimens to evaluate CHD4 expression in patients with rectal cancer, who are treated with CCRT." (PMID 31438571, 2019). "However, it is still unclear exactly how CHD4 may act as a radio-resistant regulator in rectal cancer patients." (PMID 31438571, 2019). "Furthermore, we identified the important role of CHD4 in the radio-resistance of rectal cancer." (PMID 31438571, 2019). "In conclusion, we demonstrated that the over-expression of CHD4 was negatively correlated with clinicopathological parameters, and poor responsiveness to neoadjuvant CCRT, in rectal cancer." (PMID 31438571, 2019). "Our in vitro experiments provide a new perspective on therapeutic strategies, combining radiotherapy with inhibitors of the NuRD complex, according to the CHD4 and MSI statuses of rectal cancer patients." (PMID 31438571, 2019). "Currently, a lot of previous studies have reported that genes SERPINB5, CHD4, TCN1, VNN1, EPHA4, PCSK1, and DUOX2 as prognostic biomarkers were proven to correlate with poor tumor response and survival prognosis in patients with rectal cancer receiving pCRT." (PMID 33506057, 2021). "However, there are no reports on the correlation between CHD4 expression and therapeutic responses to CCRT in rectal cancers, with respect to MSI status." (PMID 31438571, 2019).
uterine serous carcinoma (5 papers, 2013 to 2025). "Recently, whole-exome sequencing revealed high-frequency deletion of a short segment of chromosome 19 containing the MBD3 locus in uterine serous carcinoma and frequent point mutations in CHD4 in serous endometrial tumors, suggesting fundamental functions of NuRD in primary tumors." (PMID 24385926, 2013).
acute myeloid leukemia (4 papers, 2019 to 2025). Acute myeloid leukemia (AML) is a group of neoplasms arising from precursor cells committed to the myeloid cell-line differentiation. "A first-in-class inhibitor (ED2-AD101) of SMARCA5/CHD4 was recently shown to suppress cell growth in acute myeloid leukemia (AML) cells, but no inhibitors specifically targeting CHD4 are currently available for clinical use." (PMID 31921698, 2019).
autism spectrum disorder (4 papers, 2018 to 2023). A spectrum of developmental disorders that includes autism, and Asperger syndrome. "As an example, identification of de novo mutations in patients linked the FMRP partner candidates Tbl1xr1 and Chd4 to autism spectrum disorders." (PMID 36237573, 2022). "Some of these may include CHD7 causing CHARGE syndrome (MIM #214800), CHD4 as causative of Sifrim–Hitz–Weiss syndrome (MIM #603277), or CHD8 causing autism spectrum disorder (MIM #610528)." (PMID 37761804, 2023).
colon cancer (4 papers, 2015 to 2021). "In this study, CHD4 depletion was found to sensitize colon cancer cells to DNMT inhibitors in reactivating hypermethylated genes." (PMID 32577620, 2019). "It was found that depletion of CHD4 is synergistic with DNMT inhibition in reducing the viability of colon cancer cells in correlation with reactivation of tumor suppressor, suggesting that their combined inhibition may be beneficial for the treatment of colon cancer." (PMID 26075616, 2015). "To assess the role of CHD4 in CRC patients, we used colon cancer samples from the Ualcan database by The Cancer Genome Atlas to analyze the association between CHD4 mRNA expression and several clinical parameters." (PMID 33994851, 2021). "When SIRT1-Flag tagged expression plasmid was transfected into Human colon cancer HCT116 cell line, the acetylation levels of SMARCA5, MTA2, HMGA1, EGFR, CHD4 and GOT2 decreased as equal amounts of the proteins were immunoprecipitated." (PMID 28676654, 2017).
glioma (4 papers, 2019 to 2022). A benign or malignant brain and spinal cord tumor that arises from glial cells (astrocytes, oligodendrocytes, ependymal cells). "Many somatic mutations of CHD4 have been reported to be associated with different carcinomas, gliomas, medulloblastoma, hematopoietic, and lymphoid carcinomas." (PMID 33981601, 2021). "Alterations of EZH2, KMT2C, and CHD4 at the genetic or protein level could perturb an epigenetic program, leading to malignant transformation in glioma." (PMID 34996478, 2022). "HDAC-related genes upregulated in IDH1/2mut glioma include HDAC2/4/5, KDM1A, CHD4, MTA2/3, SIRT1/2, PHF21A, and BRMS1L." (PMID 34424450, 2021).
Glucose intolerance (4 papers, 2024 to 2025). Glucose intolerance (GI) can be defined as dysglycemia that comprises both prediabetes and diabetes. "While β-cell-specific loss of CHD3 alone had little effect, combined deletion of CHD3 and CHD4 caused severe glucose intolerance, impaired insulin secretion, and reduced β-cell area." (PMID 41282155, 2025). "Together, these results demonstrate that combined loss of CHD3 and CHD4 compromises β-cell survival and insulin secretory capacity, contributing to the glucose intolerance observed in Chd3/4Δβ mice." (PMID 41282155, 2025). "An inducible β-cell-specific Chd4 knockout mouse model showed that the loss of Chd4 led to glucose intolerance and impaired insulin secretion." (PMID 39057094, 2024). "Similarly, Chromodomain helicase DNA-binding protein 4 (CHD4), a subunit of the nucleosome remodeling and deacetylase (NuRD) complex, is required in mature β-cells, as its loss leads to glucose intolerance and impaired insulin secretion." (PMID 40729009, 2025). "By 10 weeks of age, the Chd4 βΚΟ male mice became severely diabetic compared to controls, displaying significantly lower body weight, significantly higher fasted and ad libitum blood glucose levels, severe glucose intolerance and dehydration due to excessive urination." (PMID 40667117, 2025).
leukemia (4 papers, 2017 to 2025). A malignant (clonal) hematologic disorder, involving hematopoietic stem cells and characterized by the presence of primitive or atypical myeloid or lymphoid cells in the bone marrow and the blood. "The discovery of a T-ALL-specific CHD4 gene expression regulation hints at a potential anti-leukemia target by perturbing the CHD4-insu element." (PMID 36624151, 2023).
non-small cell lung carcinoma (4 papers, 2019 to 2023). A group of at least three distinct histological types of lung cancer, including non-small cell squamous cell carcinoma, adenocarcinoma, and large cell carcinoma. "This study aimed to demonstrate the role of CHD4 in the development of non-small cell lung cancer (NSCLC) and determine the potential mechanisms of action." (PMID 32228507, 2020). "Downregulation of CHD4 could reduce the proliferative and migratory ability of non-small cell lung cancer (NSCLC) cells and could decrease tumorigenicity in nude mice." (PMID 36681835, 2023).
autism (3 papers, 2016 to 2021). Persistent deficits in social interaction and communication and interaction as well as a markedly restricted repertoire of activity and interest as well as repetitive patterns of behavior. "CHD4 mutations were identified in the patients with multiple neurological disorders, such as neurodevelopmental delay, cognitive disability, and autism, suggesting CHD4 protein plays a crucial role in neurodevelopment." (PMID 34109749, 2021). "For example, mutations in CHD4 (OMIM # 617159) cause neurodevelopmental delays, chromatin remodelers have been associated with cognition, Eif4e has been tightly linked with autism and autophagy with autism, brain degeneration and schizophrenia." (PMID 30534048, 2018).
breast tumor (3 papers, 2021 to 2025). "The ERα-CHD4 relationship and the pivotal role of ERα in promoting the growth of hormone-responsive breast tumor cells prompted us to examine the biological function of CHD4 in the context of ERα." (PMID 38292202, 2024). "Breast tumor growth was significantly attenuated in NSG mice bearing CHD4-KD MDA MB-231 cell xenografts." (PMID 33981601, 2021). "Moreover, CHD4 increased ERα-mediated growth of ER-positive breast tumor cells in vitro." (PMID 38292202, 2024).
CHARGE syndrome (3 papers, 2014 to 2023). CHARGE syndrome is a multiple congenital anomaly syndrome characterized by the variable combination of multiple anomalies, mainly Coloboma; Choanal atresia/stenosis; Cranial nerve dysfunction; Characteristic ear anomalies (known as the major 4 C's). "CHD4 is in the same gene family as CHD7 whose haploinsufficiency leads to CHARGE syndrome, which is a multisystem developmental disorder." (PMID 25329894, 2014).
gastric cancer (3 papers, 2012 to 2025). A primary or metastatic malignant neoplasm involving the stomach. "It has been reported that loss of CHD4 expression was observed in 56.4% of the gastric cancers and 55.7% of the CRCs." (PMID 22496748, 2012). "Significant CHD4 overexpression is observed in stomach cancer." (PMID 40004553, 2025). "CHD4 expression was detected in gastric cancers and CRCs by immunohistochemistry." (PMID 22496748, 2012).
lung adenocarcinoma (3 papers, 2022 to 2025). A carcinoma that arises from the lung and is characterized by the presence of malignant glandular epithelial cells. "In addition, the results from our study demonstrated that the mRNA expression of CHD4/6/7/8 was remarkably linked with cancer stage in patients with lung adenocarcinoma, and CHD1/2/4/6/7/9 was associated with cancer stage in patients with lung squamous cell carcinoma." (PMID 35467222, 2022). "However, low CHD4 expression was significantly correlated with poor OS and FP in all of the patients with lung adenocarcinoma, which seemed contradictory to the role of CHD4 as a tumor suppressor in other cancer types." (PMID 35467222, 2022).
melanoma (3 papers, 2021 to 2025). A malignant, usually aggressive tumor composed of atypical, neoplastic melanocytes. "RNA-seq following CHD4 silencing in melanoma cells identified more than 1000 up-regulated genes compared to 364 down-regulated genes showing that CHD4 acted primarily as a transcriptional repressor." (PMID 33741961, 2021). "ChIP-seq in melanoma cells revealed that CHD4 occupied an intronic regulatory element in PADI1 immediately adjacent to sites occupied by transcription factors CTCF and FOSL2 (AP1)." (PMID 33741961, 2021). "We performed siRNA CHD4 silencing in a collection of melanoma cells." (PMID 33741961, 2021). "This screen identified the ATPase subunit of the PBAF chromatin remodelling complex BRG1 along with CHD4, the catalytic ATPase subunits of the Nucleosome Remodelling and Deacetylation (NuRD) complex, as essential for tumour formation by all tested melanoma PDX." (PMID 33741961, 2021). "De-regulated expression of selected genes upon CHD4 silencing was confirmed by RT-qPCR on independent RNA samples in 501Mel, MM117 and SK-Mel-28 melanoma cells." (PMID 33741961, 2021). "Hence, by regulating glycolysis, CHD4 silencing or PAD1 and PAD3 expression acts to modulate melanoma cell sensitivity to BRAF inhibition." (PMID 33741961, 2021).
osteosarcoma (3 papers, 2019 to 2024). A usually aggressive malignant bone-forming mesenchymal neoplasm, predominantly affecting adolescents and young adults. "The proximity between the nucleosome remodeling ATPases CHD4 and BRG1, which are best described as components of the NuRD and P/BAF complexes, has been demonstrated in osteosarcoma and hematopoietic cells." (PMID 33770102, 2021).
schizophrenia (3 papers, 2016 to 2021). A major psychotic disorder characterized by abnormalities in the perception or expression of reality. "CHD4 mutations have also been detected in the patients with neurodevelopmental disorders, Rett syndrome, schizophrenia, and pituitary stalk interruption syndrome, among whom rare cases presented epilepsy." (PMID 34109749, 2021).